RN7SL263P (RNA, 7SL, cytoplasmic 263, pseudogene)
Gene: Miscellaneous RNA gene on chromosome 22 (23,261,782 to 23,262,071, reverse strand). Ensembl gene ENSG00000240160.
Homologues: Orthologues: chimpanzee Metazoa_SRP (98% identical), macaque Metazoa_SRP (87% identical). Paralogues in human: RN7SL1 (83% identical), RN7SL3 (83% identical), RN7SL2 (82% identical), RN7SL296P (81% identical), RN7SL507P (80% identical), RN7SL679P (80% identical), RN7SL655P (79% identical), RN7SL711P (78% identical), RN7SL735P (78% identical), RN7SL230P (78% identical), RN7SL357P (78% identical), RN7SL478P (78% identical), and 698 more.